FGF21 (fibroblast growth factor 21)
Diseases named in the same sentence as FGF21 in open-access papers (continued):
Sharing a sentence is not in itself a finding about the gene and the disease.
Hepatic steatosis (continued). "Taken together, these results strongly suggest that the circulating FGF21 level may reflect the severity of hepatic steatosis and may indicate the early onset of NAFLD progression, thus representing a candidate biomarker of metabolic disorders." (PMID 34944728, 2021). "To elucidate the role of AHNAK in preventing diet-induced hepatic steatosis, we determined whether Ahnak deficiency regulates HFD-induced production and release of hepatic FGF21." (PMID 33785868, 2021). "Previously, preclinical studies of FGF21 action on liver steatosis were performed only in males." (PMID 34943946, 2021). "Additionally, plasma levels of Fgf21 (fibroblast growth factor 21), a recently identified myokine with implications in fatty liver disease, were elevated in TRN mice (p < 0.05)." (PMID 34755487, 2021). "It was shown in preclinical models that administration of FGF21 or its mimetics and analogs reduces body weight, blood glucose levels, improves blood lipid profiles, increases insulin sensitivity, and protects from fatty liver disease in obese animals." (PMID 34943946, 2021). "Based on the resemblance in the pathological spectrums between fatty liver disease and fatty pancreas disease, it can be extrapolated that FGF21 would similarly exert an inhibitory, protective effect on the fatty pancreas and inflammation-associated PDAC development." (PMID 33668583, 2021). "FGF19 and FGF21 both depend on KLB expression in the CNS to lower hepatic steatosis." (PMID 33414764, 2020). "FGF21 clearly lowers hepatic steatosis in mice and multiple mechanisms ranging from decreases in BW, increases in beta-oxidation to increases in autophagy may play important roles." (PMID 33414764, 2020). "Nrf2 activation ameliorates methionine- and choline-deficient (MCD) diet-induced hepatic steatosis, inhibiting Cluster of differentiation 36 (CD36), Fibroblast growth factor 21 (Fgf21), and PPARα expression in the liver of mice, whereas Nrf2 deletion increases PPARα expression." (PMID 33066023, 2020). "In addition, the combination of FGF-21 with these biochemical parameters can further improve the accuracy for predicting high-grade liver steatosis than either test used alone." (PMID 31750276, 2019). "A possible explanation for the increase in FGF-21 concentration in our subjects with NAFLD may be due to a feedback-induced protective response against hepatic steatosis or an FGF-21-resistant state." (PMID 31750276, 2019). "Including FGF-21 in the biomarker panels may improve the accuracy for identifying obese and overweight children with high-grade liver steatosis." (PMID 31750276, 2019). "Despite eating, surgical re-routing of the gut may prevent weight accumulation, regulate glucose-lipid metabolism and insulin sensitivity, control a chronic inflammatory state, change the secretion pattern of FGF21 and alleviate the severity of fatty liver." (PMID 30355361, 2018). "Furthermore, induction of FOXA1 is an adaptive response to hepatic steatosis and was shown to reduce lipid accumulation in human hepatocytes as is the induction of FGF21 with its great therapeutic potential in the treatment of NAFLD." (PMID 30547786, 2018). "Similarly, it was recently reported at the 2017 Meeting of the European Association for the Study of Liver Disease that pharmacological treatment with FGF21 reduces fatty liver." (PMID 30355361, 2018). "However, HRD1 deletion protects mice from fatty liver disease largely in an Fgf21-independent manner." (PMID 30201971, 2018). "Therefore, our results can be interpreted to indicate that AMPK and p38 activation mediates the effect of FGF21 on PGC1α activation leading to alteration in fatty acid catabolism in alcoholic fatty liver." (PMID 27498701, 2016). "Hepatic induction of FGF21 by SIRT1 has been shown to protect from liver steatosis." (PMID 27669233, 2016).
Hepatic steatosis (continued). "A recent study demonstrated that loss of FGF21 induction in general control nonderepressible 2 (GNC2) knockout mice resulted in an exaggerated hepatic steatosis further supporting the notion that FGF21 is important in stimulating cellular defenses against lipid dysregulation." (PMID 27498701, 2016). "Serum FGF21 levels are elevated in non-alcoholic fatty liver." (PMID 27148532, 2016). "Based on current understanding of favourable metabolic effect of FGF‐21, exercise‐induced FGF‐21 might contribute to protect against hepatic steatosis and hepatic injury." (PMID 26648452, 2016). "This study suggests that the favorable effects of a BM extract on increasing insulin sensitivity and attenuating hepatic steatosis may be mediated by enhanced FGF21 and AMPK-Sirt1 signaling." (PMID 24189525, 2013). "Therefore, the serum FGF21 increases independently with the degree of hepatic steatosis to maintain a balance of hepatic lipid metabolism." (PMID 21949781, 2011). "Interestingly, we found that in patients with mild or moderate hepatic steatosis (HFC was in Q1–Q3), FGF21 was the strongest factors independently associated with HFC among all metabolic parameters measured." (PMID 21949781, 2011). "In summary, our study demonstrated that FGF21 was strongly correlated with the hepatic fat content in people with mild or moderate hepatic steatosis and could better reflect hepatic fat content than any known serum parameters." (PMID 21949781, 2011). "Thus, liver KLB knockdown impaired the beneficial effect of KD on ameliorating hepatic steatosis, particularly by suppressing lipogenesis, suggesting that FGF21-KLB signaling might be critical for KD-ameliorated hepatic steatosis." (PMID 38609395, 2024). "However, the mechanistic role of FGF21-KLB signaling for KD-ameliorated fatty liver remains unknown." (PMID 38609395, 2024). "Similarly, in patients with non-alcoholic steatohepatitis, FGF21 analogues ameliorate hepatic steatosis, liver stiffness and biomarkers of liver fibrosis, however the long-term effects of FGF21 in clinical outcomes remain unknown." (PMID 37818094, 2023). "In addition, FGF21 has been claimed to have beneficial regulatory effects on lipid metabolism and thermogenesis, especially in mice undergoing serious stresses such as starvation, cold exposure and hepatic steatosis." (PMID 38049769, 2023). "If this was confirmed, then FGF-21 agonists could be potentially introduced as an add-on to DAAs in specific subsets of patients, in whom the metabolic risk associated with liver steatosis remains elevated regardless of viral eradication." (PMID 37999215, 2023). "Our observations may likely explain the recent clinical findings that treatment with FGF21 analogues in patients with NASH not only reduced hepatic steatosis but also increased hepatic bile acid synthesis and further promoted cholesterol removal, lowering the risk for further hepatic lipotoxicity." (PMID 36648330, 2023). "However, adipokines (adiponectin, leptin) are thought to contribute to the anti-inflammatory effects of various hepatokines, such as apelin, adropin and fetuin-A by decreasing the local production of IL-6 and fibroblast growth factor 21 (FGF21), which prevent hepatic steatosis and fibrosis." (PMID 36830074, 2023). "Furthermore, FGF21 is vital in preventing the onset of advanced diseases, such as pancreatic ductal adenocarcinoma or hepatocellular carcinoma, by delaying the onset of the fatty pancreas, steatopancreatitis, fatty liver, and steatohepatitis." (PMID 37108717, 2023). "Additionally, FGF21 related treatments could prevent fatty liver progression and reverse the development of AFLD in mice." (PMID 36457562, 2022). "Furthermore, FGF21 may protect against hepatic steatosis by attenuating ER stress-induced VLDL receptor (VLDLR) upregulation and suppressing the maturation level of SREBP1 protein induced by ER stress." (PMID 36618930, 2022).
Hepatic steatosis (continued). "FGF21 produced by MS-275 stimulation might protect against hepatic steatosis in HFD-induced mice." (PMID 36077368, 2022). "Consequently, FGF21 is a promising therapeutic target for the treatment of fatty liver disease." (PMID 35998055, 2022). "Moreover, the logarithmically transformed FGF-21 levels were positively and significantly correlated with liver steatosis grade (B = 0.516, P < 0.001) whereas logarithmically transformed adiponectin (B = −0.217, P = 0.067) and leptin levels (B = 0.003, P = 0.978) were not." (PMID 31750276, 2019). "Therefore we consider FGF21 regulation as an adaptive response to hepatic steatosis." (PMID 30547786, 2018). "Moreover, among commonly regulated hepatic steatosis genes is FGF21." (PMID 30547786, 2018). "Thus, we investigated whether CO-induced FGF21 expression alleviates hepatic steatosis in Fgf21+/+ and Fgf21−/− mice challenged with ER stressors." (PMID 29295856, 2018). "However, excessive increases in FGF21 induced by ERRγ may have a beneficial effect on hepatic steatosis." (PMID 27455076, 2016). "Indeed, FGF21 has anti-inflammatory role in lipid lipotoxicity, where absence of FGF21 leads to severe hepatic steatosis on methionine choline deficient diet and exacerbates cardiac myopathy and oxidative stress with lipid accumulation." (PMID 26872145, 2016). "As miR‐212 was one of the most upregulated miRNA in fatty liver in the present study and FGF‐21, a central regulator for lipid metabolism, is a previously validated target gene of miR‐212, the following work was focused on the role of miR‐212 in liver steatosis." (PMID 26648452, 2016). "However, it has been reported that lower level of FGF‐21 may occur when hepatic steatosis progresses to liver inflammation and/or fibrosis." (PMID 26648452, 2016). "However, FGF21 KO mice exhibited a more severe hepatic steatosis." (PMID 27498701, 2016). "Therefore, strategies targeting the SNS activation to block FGF21-mediated excess-adipose lipolysis might be developed to prevent/treat acute alcohol-induced fatty liver disease." (PMID 26092866, 2015). "In addition, FGF21 was reported to suppress the adipogenesis-related genes in liver, FGF21 had a benefit to fatty liver disease, and the treatment of recombinant FGF21 in 3T3-L1 could increase lipolysis." (PMID 26703591, 2015). "It is also likely that, in mice fed HFD, FGF21 could be exerting an important role in the liver where MR led to the transcriptional upregulation of Pparγ gene expression which correlated with improved glucose homeostasis and decreased hepatic steatosis." (PMID 23236485, 2012). "Furthermore, we found a decrease of FGF21 in patients with severe hepatic steatosis, which might indicate the presence of hepatic injury." (PMID 21949781, 2011). "Hormones secreted by hepatocytes, termed hepatokines, include fibroblast growth factor 21 (FGF21), which regulates metabolic pathways in adipose tissue and mediates hepatic steatosis and fibrosis development." (PMID 39928502, 2025). "Notable batokines include fibroblast growth factor 21 (FGF21), which enhances glucose uptake and lipid oxidation, neuregulin 4 (NRG4), which protects against hepatic steatosis, and bone morphogenetic protein 8b (BMP8b), which enhances the thermogenic capacity." (PMID 40699742, 2025). "Previous reports have shown that Momordica charantia enhances liver FGF21 and AMPK/Sirt1 signaling to alleviate hepatic steatosis in mice." (PMID 38644407, 2024). "The promising metabolic benefits of FGF21 that contribute to the resolution of hepatic steatosis are supported by evidence from rodent models of NAFLD/MASLD and NASH/MASH, where FGF21 analogs have reduced hepatic steatosis." (PMID 39409124, 2024). "Aligned with prior studies, we validated that KD upregulates FGF21 and KLB expression, leading to a reduction in hepatic steatosis." (PMID 38609395, 2024).
Hepatic steatosis (continued). "According to the “multiple strikes” theory of NAFLD/MASLD pathogenesis, FGF21 influences several other critical processes, including oxidative stress, endoplasmic reticulum stress, mitochondrial dysfunction, and low-grade inflammation, which could help attenuate the progression of liver steatosis." (PMID 39409124, 2024). "Thus, we hypothesized that KD might ameliorate hepatic steatosis via hepatic FGF21-KLB signaling." (PMID 38609395, 2024). "FGF21 can protect against NAFLD/NASH by reducing hepatocyte stress and hepatic steatosis as well as directly protecting against inflammation and fibrosis, which is aimed at the pathological characteristics of NAFLD/NASH." (PMID 36594101, 2023). "FGF21 can mediate islet autophagy via the FGF21-AMPK-mTOR pathway in mice 100, and the effect of FGF21 on hepatic steatosis and insulin resistance in mice occurs via the FGF21-JMJD3 histone demethylase pathway." (PMID 36594101, 2023). "Taken together, our data indicate that inhibiting methylation directly at the Klb promoter promotes hepatic FGF15/FGF21/KLB signaling and subsequent fatty acid oxidation, ameliorating hepatic steatosis in mice." (PMID 37282749, 2023). "The effect of FGF21 on protecting against NAFLD/NASH is targeted on the pathological characteristics of NAFLD/NASH, including reducing hepatocyte stress and hepatic steatosis as well as directly protecting against inflammation and fibrosis." (PMID 36594101, 2023). "Studies that evaluate exogenous administration of FGF21 in obese and insulin-resistant humans show significant benefits such as weight loss, reduced blood glucose, reduced cholesterols and low-density lipoproteins, and resolution of hepatic steatosis with minimal to no side effects." (PMID 36756310, 2023). "Moreover, the finding that SN-401 robustly increases serum FGF21 levels may provide an additional secondary metabolic molecular mechanism for the observed improvements in glucose metabolism, and hepatic steatosis observed in these SN-401 treated T2D models and warrants future investigation." (PMID 35145074, 2022). "In a previous study, we demonstrated that recombinant fibroblast growth factor 21 (FGF21), which is currently in clinical development for the potential treatment of NASH, ameliorates HFD-induced hepatic steatosis by improving HIO." (PMID 36012166, 2022). "A study showed that FGF21 reduced α-SMA production by inhibiting succinate -GPR91 signaling in HSCs and improved hepatic steatosis and fibrosis in an MCD diet-induced mouse model." (PMID 36618930, 2022). "The levels of miR-22 are inversely correlated with those of FGF21 and FGFR1 in human and mouse fatty livers, and miR-22 inhibition reduces hepatic steatosis via FGF21 and FGFR1 induction." (PMID 33664851, 2021). "Characterization of phenotypic changes in Ahnak KO mice, such as reduced hepatic steatosis, decreased adiposity, and increased energy expenditure, establishes AHNAK as a novel regulator of FGF21 in modulating hepatic fatty acid metabolism." (PMID 33785868, 2021). "Characterization of the phenotypic changes in Ahnak KO mice, including reduced hepatic steatosis, decreased adiposity, and increased energy expenditure, establishes AHNAK as a novel regulator of FGF21 for the modulation of hepatic fatty acid metabolism." (PMID 33785868, 2021). "Nevertheless, clinical studies have shown that levels of circulating FGF21 are often elevated, notably in pathophysiological states, including T2DM, fatty liver diseases, and coronary heart diseases." (PMID 33668309, 2021). "The most important are: Fatty liver index (FLI), Hepatic steatosis index (HSI), SteatoTest, NAFL screening score, Cytokeratin-18 (CK18), and Fibroblast growth factor 21 (FGF21)." (PMID 32349225, 2020). "Overall, the best performance was obtained by combing FGF-21, γ-GT, and TG with the AUROC of 0.871, specificity of 82.54%, and sensitivity of 83.78% for predicting high-grade liver steatosis." (PMID 31750276, 2019).
Hepatic steatosis (continued). "Overall, the best performance was obtained by combing FGF-21, γ-GT, and TG, with an AUROC of 0.871, specificity of 82.54%, and sensitivity of 83.78% for predicting high-grade liver steatosis." (PMID 31750276, 2019). "In conclusion, this research demonstrated that administration of FGF21 reduces the production of α-SMA through inhibition of succinate -GPR91 signaling in HSCs and improves hepatic steatosis and fibrosis in an MCD diet -induce mouse model." (PMID 29444136, 2018). "Cellular stress triggers a massive increase of lipolysis in adipocytes, possibly mediated by the hormone fibroblast growth factor-21 (FGF-21), with consequent release of fatty acid in the circulation, so contributing to hepatic steatosis." (PMID 28946672, 2017). "We found that phosphor AMPK and p38 levels were severely reduced in FGF21 KO mice exposed to alcohol, indicating a link between FGF21 and AMPK- and p38-medaited PGC1α activation in alcoholic fatty liver." (PMID 27498701, 2016). "The present study suggests that FGF21 treatment reversed the development of experimental ALD and thus prevented the progression of fatty liver to advanced liver disease." (PMID 27498701, 2016). "Interestingly, FGF21 overexpression partially restored the expression of PPARα and its target genes, Acox1, Hmgcs2 and Cpt1a in Creb3l3−/− mice, which might have helped to improve the hepatic steatosis." (PMID 27301791, 2016). "In line with this, a recent paper demonstrated that adipose tissue specific CGI-58 knockout mice are protected from fasting-induced hepatic steatosis due to decreased NEFA delivery to the liver, which led to impaired CREBH activation and FGF21 expression." (PMID 27301791, 2016). "Fibroblast growth factor 21 (FGF-21) had the function of reducing blood glucose, lipid and insulin levels, reversing liver steatosis and improving insulin sensitivity." (PMID 26121037, 2015). "Nrf2-null mice exhibited more severe hepatic steatosis, while Keap1-KD mice exhibited less, along with decreased CD36 and Fgf21 expression, suggesting Nrf2 negatively regulate lipogenesis and hepatic lipid accumulation." (PMID 24224011, 2013). "In this study, we demonstrated that BM-V reduced plasma FGF21 levels and hepatic FGF21 content, and attenuated HFD-induced liver steatosis, while BM-V also significantly enhanced peripheral insulin sensitivity." (PMID 24189525, 2013). "Therefore we speculated that the decrease of FGF21 in patients with severe hepatic steatosis might also be explained by the hepatic cell injury or death caused by lipoxicity and hepatic inflammation, so that the remaining hepatic cells were unable to produce as much FGF21 as needed." (PMID 21949781, 2011). "Activation of PPARα by WY14643 ameliorated hepatic steatosis through increasing lipids oxidation promoting genes CYP4A10, CYP4A14, FGF21, adiponectin, SIRT1 and PGC-1α expression, and suppressing fatty acid synthesis promoting genes FAS and PI3K expression." (PMID 22208561, 2011). "This review explores current and emerging TG-lowering therapies, including fibrates, omega-3 fatty acids, pemafibrate, and novel agents such as pegozafermin (an FGF21 analog), and APOC3 and angiopoietin-like protein 3 (ANGPTL3) inhibitors, in the context of hepatic steatosis and MASLD." (PMID 42206171, 2026). "FGF21 and its analogues activate FGFR1c/β-Klotho signaling, promoting fatty acid oxidation, WAT browning, and PGC-1α-driven thermogenesis, with early trials showing improvements in lipid profiles and hepatic steatosis." (PMID 41596403, 2026). "Data from experimental studies have shown that FGF-21, acting through on its receptor (FGFR1) on the cell membrane with β-Klotho as co-receptor, increases fatty acid β-oxidation and decreases de novo lipogenesis, thereby attenuating hepatic steatosis." (PMID 40465044, 2025).